PROM1 (prominin 1)
Diseases named in the same sentence as PROM1 in open-access papers (continued):
Sharing a sentence is not in itself a finding about the gene and the disease.
glioblastoma (501 papers, 2006 to 2025). The most malignant astrocytic tumor (WHO grade IV). "GICs are cellular subpopulations of glioblastoma that express neural stem and progenitor cell markers, such as PROM1 (encoding CD133), OLIG2, and SOX2." (PMID 34214250, 2022). "For example, we analyzed using the GlioVis Portal the correlation between mRNA expression of LIS1 and PROM1 (CD133 encoding gene) in glioblastoma samples from the Ivy Glioblastoma Atlas Project (Ivy GAP)." (PMID 31750243, 2019). "Furthermore, PROM1, a marker associated with tumor stemness and glioblastoma progression, showed a positive correlation with MKI67 in some tumor models." (PMID 40917877, 2025). "Glioblastoma CSCs (CD133+/Prominin-1) induced by radiotherapy can increase resistance by activating DNA checkpoints and repair pathways." (PMID 40548119, 2025). "CD133 (PROM1) marks a subpopulation of glioblastoma stem cells with potent tumour-initiating and chemoresistant properties." (PMID 41179304, 2025). "In glioblastoma CSCs, VPA downregulates the expression of stemness genes Prominin 1 (PROM1, which encodes CD133), NANOG, and POU Class 5 Homeobox 1 (POU5F1, also known as OCT4) and increases differentiation markers." (PMID 39851500, 2025). "For example, radiation therapy-induced glioblastoma CSCs (CD133+ /Prominin-1) formation supports radioresistance by activating DNA checkpoints and repair pathways." (PMID 38347575, 2024). "Glioblastoma CSCs (U87) were discovered in 2002, and they had been characterized using the PROM1 marker (formerly known as cluster of differentiation 133 - CD133) by 2004." (PMID 39830209, 2024). "CD133/prominin-1 is a pentaspan transmembrane glycoprotein overexpressed in various solid tumors, including colorectal and glioblastomas." (PMID 37509347, 2023). "Prominin-1, or CD133, is a widely explored CSC biomarker associated with normal neural stem cells, and thus is commonly used in glioblastomas, together with other CSC markers such as CD24, CD44, CXCR4, Oct3/4, and Nanog." (PMID 38139085, 2023). "By measuring the expression of PROM1 in malignant cells, we observed higher levels in cells from pediatric glioblastomas." (PMID 35970913, 2022). "Here, we sought to investigate the presence of a quiescent PROM1+ subpopulation in samples of adult and pediatric glioblastomas." (PMID 35970913, 2022). "In the present study, we showed that, among the three DNA methyltransferases, the silencing of DNMT3A maintained the expression of PROM1 and the number of CD133‐positive glioblastoma cells, even in the presence of BMP‐4." (PMID 34214250, 2022). "In addition to cellular components, it is important to describe that prominin-1 is released in association with membrane vesicles into the cerebrospinal fluid, and their amount is elevated in glioblastoma patients, which could impact the surrounding cells in the cancer microenvironment and beyond." (PMID 34476215, 2021). "CD133 (prominin-1) is a stem cell marker, also expressed by cancer stem cells of many tumor entities including glioblastoma." (PMID 31798595, 2019). "After the initial characterization as a CSC marker in glioblastoma, the surface protein CD133 (also known as prominin-1) was utilized in the identification and/or isolation of CSC in a wide spectrum of solid tumors." (PMID 28320418, 2017). "CD133 (prominin 1) expression was described and used for isolation of CSCs from various solid tumors including glioblastoma, prostate, colon, lung, pancreatic, and ovarian cancers and melanoma." (PMID 27418931, 2016). "Our group of cerebellar PAs was also characterized by elevated levels of PROM1 expression, which in glioblastoma is considered as a molecular factor of poor prognosis, and in proneural glioblastoma seems to be the potential target of anti-angiogenic therapy." (PMID 26497896, 2015).
glioblastoma (continued). "CD133 or prominin-1 was proposed as a biomarker of tumor progression/initiation cells described in glioblastoma, but it appeared later to be insufficient as CD133-negative cells were also able to initiate tumors." (PMID 26078762, 2015). "Prominin-1 (CD133) is a commonly used cancer stem cell marker in central nervous system (CNS) tumors including glioblastoma (GBM)." (PMID 25184684, 2014). "PROM1 is believed to identify tumor-initiating cancer stem cells in a wide range of cancer types including leukemia, breast and glioblastoma (GBM), the most common malignant brain tumor." (PMID 25184684, 2014). "Several investigators found that PROM1 is a target for Wnt signaling regenerative pathways in many cell lines including malignant melanoma and glioblastoma cells." (PMID 25452936, 2014). "CD133 (prominin-1), a neural stem cell (NSC) marker implicated in brain tumors, notably glioblastoma, was highly expressed in our material." (PMID 22995409, 2012). "CD133/prominin-1 is a pentaspan transmembrane glycoprotein overexpressed in various solid tumours including colorectal and glioblastomas." (PMID 18542072, 2008). "Coexpression of nestin and CD133 (also known as prominin-1) is considered to be a marker for cancer stem cells (CSCs); this fact was experimentally proven in glioblastoma multiforme and malignant melanoma." (PMID 18925963, 2008). "Interestingly, in proneural glioblastoma-like tumor cells, prominin-1 is expressed by the endothelium that supports microvascular proliferation and accelerates tumor growth." (PMID 34476215, 2021). "Recently, a prominin-1–AKt–Wnt signaling axis in glioblastoma tumor-initiating cells was indeed described, leading to the hypothesis that prominin-1 may act as a putative surface receptor." (PMID 34476215, 2021). "As glioblastoma has a sub-population of stem cells capable of self-renewal and radiotherapy resistance, the response of prominin-1/CD133 to ATRA in U87MG may potentially serve as a GBM cell line model for targeted differentiation strategies." (PMID 34207434, 2021). "CD133 (Prominin-1) was originally described as a CSC marker for glioblastoma." (PMID 33233552, 2020). "In particular, transcriptomic analyses showed a mesenchymal profile for periventricular glioblastoma stem-like cell line, with overexpression of VEGFC and CHI3L1 and a proneural profile for cortical glioblastoma stem-like cell line with overexpression of PROM1, DLL3, and BCAN." (PMID 26637806, 2016). "Included is at least one transcript, PROM1, encoding the CD133 cell surface marker, which has been classified as a biomarker of brain tumor stem cells defined as those cells responsible for giving rise to rapidly proliferating, serial transplantable glioblastomas in immunocompromised mice." (PMID 20423517, 2010). "Lastly, further characterization of the enriched stem cell-like state compartment in glioblastomas with a mesenchymal transition revealed an increased abundance of stem cell markers SOX2, PROM-1, and Nestin." (PMID 38244080, 2024). "Pharmacological (PAG) inhibition of CTH on human glioblastoma cells results to lower Glioblastoma Stem Cell (GSC) formation and lower mRNA expression of stem cell markers (i.e, PROM1, NOX4)." (PMID 37300955, 2023). "Increased PROM1, SOX2, Fibronectin, and RPSA transcripts level were also observed in clinical grade IV glioblastoma tissues compared to normal tissue." (PMID 36497426, 2022). "Since recruitment of DNMT3A by the pmx‐1b isoform of PRRX1 leads to GIC differentiation through the epigenetic regulation of PROM1 gene expression, pmx‐1b and DNMT3A are potentially interesting targets for the treatment of glioblastoma." (PMID 34214250, 2022). "GSCs from IDH-wild type glioblastomas are characterized to express PTPRZ16, Sox2 and Nanog13, CD9, PROM1 (CD133), PDGFRA and OLIG214." (PMID 36348001, 2022).
glioblastoma (continued). "Although the CpG sites in the PROM1 promoter P1 region are hypomethylated in CD133‐positive glioblastoma cells, they are highly methylated in CD133‐negative glioblastoma and in normal neural tissues." (PMID 34214250, 2022). "A growing body of evidence supports the presence of a population of cells in glioblastoma (GBM) with a stem cell-like phenotype which shares certain biological markers with adult neural stem cells, including expression of SOX2, CD133 (PROM1), and NES (nestin)." (PMID 36333778, 2022). "Here, we demonstrate that U87 glioblastoma 3D neurospheres culture conditions can partially recapitulate the CSC chemoresistance and invasive molecular signature by increasing PROM1, SOX2, and NANOG expression." (PMID 36497426, 2022). "For instance, Prominin 1 or CD133 is a CSC biomarker, which is highly expressed in breast cancer, ovarian cancer, colorectal cancer, and glioblastoma as well as in ESCs and human preimplantation embryos." (PMID 34968365, 2021). "Various CSC surface markers have been described in glioblastomas, including the most frequently represented CD133 (PROM1), A2B5, and CD15 (stage-specific embryonic antigen 1)." (PMID 26637806, 2016). "An attempt to identify molecular profiles specific for treatment resistance to the concomitant radio-chemotherapy with TMZ in glioblastoma eluted a self-renewal signature, homeobox (HOX) genes, which include prominin-1 (CD133)." (PMID 24212792, 2011). "Additionally, PAG under baseline conditions can significantly reduce the formation of glioblastoma stem cells derived from human GBM cells and downregulate the mRNA expression of genes involved in stem cell formation such as PROM1 and NOX4." (PMID 37300955, 2023). "Combining this classification with the expression of PROM1, we identified a population of non-cycling PROM1+ cells, amounting to 11% of adult and 16% (313 cells) of pediatric malignant glioblastoma cells." (PMID 35970913, 2022). "In this study, we correlated glioblastoma locations with the expression of five mesenchymal genes (VEGFC and its receptor FLT4, HGF and its receptor MET, and CHI3L1) and five proneural genes (PROM1, NOTCH1, DLL3, PDGFRA, and BCAN)." (PMID 26637806, 2016). "In particular, in contrast with PV-FP and PV-O subtype, PV-T glioblastomas were characterized by a high expression of the mesenchymal marker VEGFC and the proneural and CSC markers NOTCH1 and PROM1 that could be potential targets for specific therapies." (PMID 26637806, 2016). "Prominin1 (Prom1, also known as CD133 in human) has been widely used as a marker for cancer stem cells (CSCs), which self-renew and are tumorigenic, in malignant tumors including glioblastoma multiforme (GBM)." (PMID 19718438, 2009). "To further characterize the population of 313 malignant non-cycling PROM1+ cells from pediatric glioblastomas, we compared their expression levels with 548 non-cycling PROM1- cells, and with 523 cycling PROM1+ cells and we identified specific sets of marker genes." (PMID 35970913, 2022). "In addition, Sihito and colleagues demonstrated that hormone receptor-negative breast cancer patients, mainly relapsing primarily to the brain, displayed higher expression of nestin and CD133 (prominin-1) in metastases, both of which are regarded as cancer stem cell (CSC) markers of glioblastoma." (PMID 33182375, 2020). "CD133 (cluster of differentiation 133 or human prominin-1), a marker that was first identified on the cell surface of CD34+ hematopoietic stem cells, has also been used to isolate populations of CSCs from glioblastoma, prostate, pancreas, ovarian, colon, lung and liver cancer." (PMID 31426611, 2019).
colon carcinoma (415 papers, 2008 to 2026). "One of recent report has shown that Lin28B promotes migration, invasion, and transformation by associating and repressing LGR5 and PROM1 mRNAs that are essential for colon cancer progression." (PMID 27821801, 2016). "It will be of great interest to determine if decreased Prom1 presence or activity has a role in the relationships between diabetes or obesity and risk for colon cancer in humans." (PMID 25452936, 2014). "PROM1 gene was found to be a target of the MLL fusion-associated gene AF4 (MLL-AF4) in human colon cancer Caco-2 cells and in some MLL cells, where its transcription is upregulated through H3K79 methylation and the presence of an intragenic H3K79me2/3 enhancer element." (PMID 38532366, 2024). "CD133/prominin-1, a pentaspan transmembrane glycoprotein, has been initially described as a surface antigen specially to human hematopoietic stem cells and CSCs with CD 133 positivity have been implicated in tumor progress as identified in tumor growth of pancreatic and colon cancers." (PMID 21054902, 2010). "CD133 (Prominin-1) is a transmembrane molecule identified as a cancer stem cell marker in various tumor entities, including colon cancer." (PMID 38607092, 2024). "Two sets of membrane markers have emerged as the most useful for the identification of colon cancer stem cells: CD133 (Prominin-1) and CD144." (PMID 29652830, 2018). "Previous studies have shown that the colon cancer stem cells isolated from HCT116 cells express high levels of PROM1 (CD133), CD44, EPCAM, SOX2, c-MYC, and NANOG." (PMID 29507661, 2018). "It will be of great interest to determine if PROM1 presence or activity is reduced in human IBD and particularly in IBD-associated dysplasia and colon cancer." (PMID 25452936, 2014). "The cell surface marker CD133, also known as prominin-1, is widely used as a CSCs marker in various tumors, including leukemia, lung cancer, colon cancer and brain cancer." (PMID 24940615, 2014). "CD133/prominin-1 as a transmembrane pentaspan protein was found to present in many solid tumors such as brain cancer, prostate cancer, and colon cancer." (PMID 24653835, 2014). "The stemness associated marker Prominin 1/CD133 was earlier reported to be decreased at mRNA and AC133 protein epitope level in colon cancer tissue by NSAID; and now further confirmed by re-analyses of the same but extended patient material." (PMID 25340937, 2014). "Prom1/CD133 has been identified in colorectal, hepatocellular, and pancreatic cancer as a cancer stem cell marker and has been used as such to predict colon cancer recurrence in humans." (PMID 25452936, 2014). "The prominin-1-based exosomal isolation protocol was then successfully employed to isolate exosomes from the serum-free culture medium of another prominin-1-expressing cancer cell line, Caco-2 colon carcinoma." (PMID 23767874, 2013). "We found that prominin-1-immunomagnetic selection resulted in isolation of cancer exosomes also from human prominin-1-expressing Caco-2 colon carcinoma cells." (PMID 23767874, 2013). "Prom1 has been utilized extensively to identify and enrich CSCs from many tumors, including lung cancers, colon cancers, hepatocellular carcinomas, and brain tumors, using the specific anti-Prom1 antibody that recognizes the glycosylated-form of Prom1." (PMID 19718438, 2009). "In agreement with this hypothesis, it was reported that sodium butyrate stimulated colon cancer cell differentiation as well as the downregulation of the cellular expression of prominin-1." (PMID 39881297, 2025). "Elevated levels of HIF-1α and HIF-2α were shown to simulated the transcription of the PROM1 gene at the P5 promoter in colon cancer cells; specifically, it was initiated by the binding of the HIF-1-Elk1 complex to the E-twenty-six (ETS)-binding motif present in P5." (PMID 38532366, 2024).
colon carcinoma (continued). "CD133 (also known as human Prominin-1) is a five-transmembrane molecule which has been identified as a cancer stem cell marker in various tumor entities, including colon cancer." (PMID 29100290, 2017). "We hypothesize that the Wnt signaling regenerative pathway results in dysregulation of Prom1 expression and subsequent changes in intestinal mucosal repair, and hence may be relevant to colon cancer development in IBD." (PMID 25452936, 2014). "However, PROM1 expression in colon cancer in humans was found to be predictive of increased colon cancer recurrence." (PMID 25452936, 2014). "Furthermore, CD133 (Prominin 1) has been used as a colon cancer stem cell marker, and it has also been suggested as a reliable marker for intestinal stem cells." (PMID 22046368, 2011). "Recently, CD133 (prominin-1: PROM1), a 5-transmembrane glycoprotein, was identified as an important marker representing a subset population of cancer stem-like cells (CSCs) in leukemia, retinoblastoma, colon cancer, prostate carcinoma, brain tumor, and hepatoma." (PMID 18509505, 2008). "Protein expression of CSC-markers prominin-1 and CD44 antigen was significantly higher for BKZ-2 and BKZ-3 in comparison to well-established colon carcinoma cell lines." (PMID 32927768, 2020). "CD133, also known as prominin-1 or AC133, is a 7-transmembrane surface maker of cancer stem cells, especially in colon cancer." (PMID 28915611, 2017). "In colon cancer, tumors with constitutive LIN28B expression exhibit increased expression of colorectal stem cell markers, LGR5, KIT and PROM1 (CD133)." (PMID 29064439, 2017). "The addition of such moieties to peptides often disconnects transcript levels from the amount detected by antibodies (e.g. Prominin-1/CD133 transcripts and the CD133 (AC133) epitope in colon cancer CSCs)." (PMID 23308131, 2013). "As the authors point out, prominin-1 could be considered as a therapeutic target for controlling cancer growth and metastasis in anti-EGF receptor drug-resistant colon cancer." (PMID 39881297, 2025). "As Prominin-1 and CD166 have shown colocalization at membrane level in colon carcinoma cells, it may be that Prominin-1 undergoes transport in a similar manner." (PMID 39353897, 2024). "In this way, LIN28B promotes transformation and migration in colon cancer through LGR5, PROM1, and CDX2 mRNAs, promotes stemness and EMT in gastric cancer through NRP-1 mRNA, inhibits apoptosis in ovarian cancer through AKT2 mRNA, and promotes migration in neuroblastoma through MYCN-induced mRNAs." (PMID 37370851, 2023). "In addition, we saw increased expression of stemness markers and putative markers of colon cancer–initiating cells such as CD44 (Cd44) and CD133 (Prom1)." (PMID 35947664, 2022). "The physiologic role of Prom1 in intestinal inflammation related to colon cancer development is not known." (PMID 25452936, 2014). "In colon cancer, both PROM1 positive and PROM1 negative cells are capable of being tumorigenic." (PMID 25452936, 2014). "In addition, colon tumors displayed an overall expression of prominin-1, suggesting that also in mouse, prominin-1 expression is not restricted to a (cancer) stem cell state." (PMID 20808829, 2010). "Moreover, there is increasing evidence that Prom1-negative cancer cells from GBMs, colon cancers, and the Daoy medulloblastoma cell line can form tumors when transplanted in vivo." (PMID 19718438, 2009).